EDC3 (enhancer of mRNA decapping 3)
Description:
Binds single-stranded RNA. Involved in the process of mRNA degradation and in the positive regulation of mRNA decapping. May play a role in spermiogenesis and oogenesis.
Synonyms: LSM16; YJDC; YJEFN2; FLJ21128; hYjeF_N2-15q23; MRT50
Tractability: Small molecule: a structure with a bound ligand is known; it has a high-quality binding pocket. PROTAC: ubiquitination databases record sites on it; its protein half-life has been measured.
Gene: Protein-coding gene on chromosome 15 (74,630,557 to 74,696,292, reverse strand). Ensembl gene ENSG00000179151.
Subcellular location: Cytoplasm, P-body
Subcellular location (Human Protein Atlas): Cytoplasmic bodies
Pathways (Reactome):
Metabolism of RNA: mRNA decay by 5' to 3' exoribonuclease
Gene Ontology:
Molecular function: identical protein binding; protein binding; mRNA binding; RNA binding
Biological process: deadenylation-dependent decapping of nuclear-transcribed mRNA; deadenylation-independent decapping of nuclear-transcribed mRNA; nuclear-transcribed mRNA catabolic process, deadenylation-dependent decay; P-body assembly
Cellular component: cytoplasmic ribonucleoprotein granule; membrane; cytosol; P-body; RNA decapping complex
Genetic constraint (gnomAD): Loss-of-function variants: 20 observed, 44.33 expected, observed/expected ratio (o/e) 0.45, 90% interval 0.32 to 0.66. The synonymous counts are far from expectation, so gnomAD's model fits this gene poorly and the ratio says little. Missense variants: 444 observed, 672.4 expected, observed/expected ratio (o/e) 0.66, 90% interval 0.61 to 0.71. Synonymous variants: 206 observed, 257.93 expected, observed/expected ratio (o/e) 0.8, 90% interval 0.71 to 0.9.
Homologues: Orthologues: chimpanzee EDC3 (99% identical), macaque EDC3 (98% identical), pig EDC3 (97% identical), dog EDC3 (96% identical), rat Edc3 (96% identical), mouse Edc3 (96% identical), guinea pig EDC3 (95% identical), tropical clawed frog edc3 (77% identical), zebrafish edc3 (69% identical), Drosophila melanogaster Edc3 (34% identical), Caenorhabditis elegans edc-3 (21% identical).
Diseases named in the same sentence as EDC3 in open-access papers:
EDC3 is named in the same sentence as 12 diseases in open-access papers, as found by Europe PMC text mining. Sharing a sentence is not in itself a finding about the gene and the disease. The quoted sentences say what the papers report.
Intellectual disability (2 papers, 2018). "Previously, we have associated a homozygous variant in EDC3 with autosomal recessive intellectual disability." (PMID 29685133, 2018). "In a previous study, we identified a homozygous variant in EDC3 in two siblings with mild non-syndromic intellectual disability." (PMID 29685133, 2018). "The upregulation of lncRNAs in EDC3 knockdown SKNBE cells might hint towards a potential causative correlation with the intellectual disability presented by our patients." (PMID 29685133, 2018). "Importantly, in a previous study, we identified a homozygous variant in EDC3 (c.161T>C; p.Phe54Ser) in two children of a consanguineous family affected by mild non-syndromic intellectual disability, indicating that EDC3 and DCP2 contribute to neuronal functions." (PMID 29685133, 2018). "More research is needed to validate these findings on EDC3 function as well as increase our understanding of mRNA degradation pathways and their potential role in intellectual disability." (PMID 29685133, 2018). "In order to obtain insights into the functional consequences of EDC3 impairment and its potential effect on intellectual disability, we performed integrative bioinformatics analyses on the SKNBE transcriptome data." (PMID 29685133, 2018). "The accumulation of ARE-containing mRNAs further supports the role of EDC3 in mRNA decapping and might contribute to the intellectual disability phenotype observed in our patients." (PMID 29685133, 2018). "Thus, the analysis of lymphoblastoid cell lines might not provide an explanation of the observed intellectual disability of the two patients with the EDC3 variant (c.161T>C; p.Phe54Ser)." (PMID 29685133, 2018).
lung carcinoma (2 papers, 2020 to 2025). "Although several of the selected early‐stage ADC‐specific proteins have been reported to play a role in tumorigenesis in various cancer types, EDC3 and NT5C3A have not been implicated in lung cancer." (PMID 32536039, 2020). "Notably, several of these CpG sites (SNORD93, NWD1, EDC3) have been associated with COPD33, which is an established independent risk factor for lung cancer in both smokers and never smokers." (PMID 40236422, 2025).
autosomal recessive intellectual disability (1 paper, 2021). "Mutations in EDC3 have been identified in autosomal recessive intellectual disability, indicating its crucial role in neurodevelopment." (PMID 34922566, 2021).
insulinoma (1 paper, 2016). "In this study, we provide the first demonstration that 2-DG reduces intracellular insulin which was increased by melatonin via autophagy and EDC3 in insulinoma INS-1E cells." (PMID 27493704, 2016). "Lastly, to confirm the relationship of insulin production with autophagy and EDC3 protein, we investigated whether the mTOR inhibitor, rapamycin, induced autophagy and expression of GRP78/BiP and EDC3 proteins in rat insulinoma INS-1E cells." (PMID 27493704, 2016).
prostate carcinoma (1 paper, 2024). A carcinoma that arises from epithelial cells of the prostate gland. "In prostate cancer cells, dephosphorylation of EDC3 promotes the localization of EDC3-containing P-bodies and increases the P-body number." (PMID 39046443, 2024). "Of note, EDC3 and LSM14A compete for binding to the P-body core protein DDX6, and P-body formation still occurs constitutively in EDC3 KO prostate cancer cells." (PMID 39046443, 2024).
cancer (2 papers, 2020 to 2022). A tumor composed of atypical neoplastic, often pleomorphic cells that invade other tissues. "EDC3 plays an important role in regulating RNA decapping and destruction in cancer progression, and it can also promote tumor growth and invasion." (PMID 35281269, 2022).
tumor (2 papers, 2022 to 2023). "It has been recently reported that the phosphorylation of Edc3, a P-body component, has an effect on tumor growth and invasion through controlling P-bodies formation and dynamics." (PMID 37762007, 2023).
infection (1 paper, 2025). The state of being infected such as from the introduction of a foreign agent such as serum, vaccine, antigenic substance or organism. "To evaluate whether EBOV replication depends on decapping components other than EDC4, we tested the impact of knockdowns of DCP1A, B and DCP2 and accessory decapping protein EDC3 on infection efficiency." (PMID 41006235, 2025).
respiratory diseases (1 paper, 2025). "Previously identified smoking-related CpG sites that were also linked to smoky coal combustion – annotated to genes such as AHRR, SNORD93, NWD1, EDC3, STK24, ZDHHC14, HIF3A – converge on key pathways involved in pollutant response, respiratory diseases, and carcinogenesis." (PMID 40236422, 2025).
EDC3 also shares sentences with these, for which no sentence is quoted: chronic obstructive pulmonary disease (1 paper); neuroblastoma (1); ZIKV infections (1).